GNB3 (G protein subunit beta 3)
Diseases named in the same sentence as GNB3 in open-access papers (continued):
Sharing a sentence is not in itself a finding about the gene and the disease.
retinal degeneration (3 papers, 2020 to 2025). Degeneration of the retina. "Knockout mutation of Nrl leads to the loss of rod cells while mutations in Gnb3, Cnga1, and Cngb1 have been shown to lead to night blindness in humans and retinal degeneration in chickens." (PMID 36576130, 2022). "In addition, it was revealed that a naturally occurring mutation in GNB3 results in retinal degeneration in chickens." (PMID 32290826, 2020). "It is worthwhile to investigate the chronic activation of ER stress/eIF2 signaling in regulating the expression of Gnb3 and Edn2, as well as their downstream interactions in progressive ocular disorders and severe retinal degeneration." (PMID 39503290, 2025).
Anxiety (2 papers, 2010 to 2017). Intense feelings of nervousness, tension, or panic often arise in response to interpersonal stresses. "The relationship between subjects with ulcers or H. pylori infection and GNB3 polymorphism has not been reported, and the reported relationships between dyspepsia and diet, stress, anxiety, or H. pylori are not conclusive." (PMID 20102604, 2010).
breast carcinoma (2 papers, 2004 to 2022). "Some studies associate the polymorphism GNB3-C825T with cholangiocarcinoma and thyroid carcinoma, but another study discarded a relationship with the risk for breast cancer." (PMID 35565241, 2022). "The C825T polymorphism in GNB3 apparently does not influence the carcinogenesis of breast cancer, which is also true for the Apo E polymorphism." (PMID 15138483, 2004).
end-stage renal disease (2 papers, 2017 to 2022). "However, there are observations, in which no apparent connection between polymorphism of GNB3 and reduction in GFR, or the occurrence of end-stage renal failure, is found." (PMID 27988909, 2017).
ischemic stroke (2 papers, 2012 to 2013). A stroke disorder caused by obstruction of blood flow to the brain, due to thrombotic (local blood clot formation) or embolic (due to a blood clot or other material traveling from another site) event. "Five studies regarding the association of the GNB3 C825T polymorphism and ischemic stroke were identified while one was regarding cerebral hemorrhage and the other two included ischemic stroke or cerebral hemorrhage cases." (PMID 23799054, 2013). "Besides, the GNB3 825T allele was found to significantly increase the risk of clinical ischemic stroke in Caucasians, but not subclinical cerebral infarct." (PMID 23799054, 2013).
lung disease (2 papers, 2017 to 2022). "A previous study reported that GNB3 polymorphisms are associated with lung disease." (PMID 35321408, 2022). "Previous studies suggest that ADRB2, GNB3, TH, and GSTP1 polymorphisms are associated with various lung diseases." (PMID 28212552, 2017).
night blindness (2 papers, 2020 to 2022). Inability to see clearly in dim light. "A homozygous missense variant in GNB3 results in a unique stationary retinal disorder with dual anomalies in visual processing, night blindness and photophobia." (PMID 32290826, 2020).
pancreatic cancer (2 papers, 2022 to 2023). "GNB3, PPP2R3B and TSC1 were highly expressed in the LRS group, suggesting that these genes may be tumor suppressors of pancreatic cancer." (PMID 37124502, 2023).
pulmonary edema (2 papers, 2017 to 2022). Accumulation of fluid in the lung tissues causing disturbance of the gas exchange that may lead to respiratory failure. "He and colleagues further demonstrated that GNB3 polymorphisms may protect against high altitude pulmonary edema progression." (PMID 35321408, 2022).
renal failure (2 papers, 2022 to 2023). "In contrast, among patients with T1DM as the underlying cause of renal failure, the distribution of GNB3 genotypes was equal." (PMID 36077181, 2022).
schizophrenia (2 papers, 2018 to 2023). A major psychotic disorder characterized by abnormalities in the perception or expression of reality. "Likewise, the detection of a link between schizophrenia-related sleep disorders and genes implicated in neurotransmitter metabolism (TH and HNMT) and signal transduction (GNB3 and BTBD9) emphasizes the central role of neurotransmission disturbances in the emergence of schizophrenia symptomatology." (PMID 29587340, 2018). "Among the 7 DEGs, the TNC gene was the only gene that decreased with schizophrenia and showed a positive correlation with PI (16:0/20:4), while the other 6 DEGs (COL1A2, COL6A2, DDIT4, FGF17, GNB3, and PDGFRB) increased with schizophrenia and showed a negative correlation with PI (16:0 /20:4)." (PMID 37143779, 2023).
viral infection (2 papers, 2022 to 2025). "The G-protein subunit Beta 3 (GNB3) gene has been identified as a potential modulator of immune responses in various conditions, including viral infections." (PMID 40543387, 2025). "With regard to allograft survival, we detected no GNB3 genotype-dependent differences in the generation of de novo anti-HLA DSAs, the occurrence of different types of rejection, or the occurrence of bacterial or viral infection as important posttransplant complications." (PMID 36077181, 2022).
achromatopsia (1 paper, 2011). Achromatopsia (ACHM) is a rare autosomal recessive retinal disorder characterized by color blindness, nystagmus, photophobia, and severely reduced visual acuity due to the absence or impairment of cone function. "Humans homozygous for severely mutated GNB3 genes are therefore more likely to suffer from a complex syndromic disorder e.g. cone-rod dystrophy or achromatopsia, with a kidney and possibly other abnormalities in other key tissues." (PMID 21887213, 2011).
Astigmatism (1 paper, 2023). A type of refraction error associated with abnormal curvatures on the anterior and/or posterior surface of the cornea. "The strongest association for AW was identified for a SNP (rs5442, p = 1.9x10-15) within the GNB3, a gene also associated previously with central retinal vein calibre, but also multiple ocular phenotypes such as refractive error, macular thickness and corneal astigmatism." (PMID 36757925, 2023).
bacterial pneumonia (1 paper, 2022). Acute infection of the lung parenchyma caused by bacteria (e.g., Streptococcus pneumoniae, Haemophilus influenzae, Chlamydia pneumoniae, Mycoplasma pneumoniae, and Legionella pneumophila). "Since P. multocida mainly causes pneumonia in goats and sheep, GNB3 may also play a role in bacterial pneumonia." (PMID 35321408, 2022).
Blindness (1 paper, 2011). Blindness is the condition of lacking visual perception defined as a profound reduction in visual perception. "Lack of GNB3 signalling causes reduced phosphorylation activity of ERK2 and AKT leading to severe pathological phenotypes such as blindness and renal abnormalities in rge chickens." (PMID 21887213, 2011).
breast tumors (1 paper, 2022). "For instance, the GNB3 825C>T polymorphism might influence development of metastasis in low-grade breast tumors." (PMID 35494074, 2022).
coronary artery stenosis (1 paper, 2023). "Our findings suggest that male dialysis patients carrying the TT genotype of GNB3 are at higher risk of left ventricular dilatation and that dialysis patients carrying the TT/TT genotype of GNAQ are prone to coronary artery stenosis and severe cardiovascular events." (PMID 37894940, 2023).
diabetic nephropathy (1 paper, 2022). "Among the subset of recipients with T2DM we found a relationship between the TT genotype of the GNB3 polymorphism and renal complications associated with that disease, such as diabetic nephropathy resulting in ESRD." (PMID 36077181, 2022).
dyspepsia (1 paper, 2010). An uncomfortable, often painful feeling in the stomach, resulting from impaired digestion. "This study evaluated GNB3 C825T polymorphism in a cohort comprising people with dyspepsia and healthy controls who visited a health care unit for annual health check-up." (PMID 20102604, 2010). "In the present study we clarified the association between GNB3 gene polymorphism and dyspepsia in a large population of Japanese subjects who visited a hospital for annual health check-up." (PMID 20102604, 2010). "The homozygous GNB3 825T allele influences the susceptibility to EPS-like dyspepsia." (PMID 20102604, 2010). "Homozygous GNB3 825C status has been associated with unexplained dyspepsia in a German population." (PMID 20102604, 2010). "In this study, we examined subjects who underwent an annual health check-up and investigated the relationship between the GNB3 gene (C835T) and dyspepsia in the Japanese population." (PMID 20102604, 2010). "The GNB3 genotype distribution in subjects without dyspepsia was 191 CC (25.1%), 368 TC (48.4%), and 202 TT (26.5%) and 17 CC (25.0%), 29 TC (42.6%), and 22 TT (32.4%) in subjects with dyspepsia." (PMID 20102604, 2010). "The GNB3 genotype distribution in subjects without dyspepsia (controls) of 191 CC (25.1%), 368 CT (48.4%), and 202 TT (26.5%), and 17 CC (25.0%), 29 CT (42.6%), and 22 TT (32.4%) in subjects with dyspepsia was also compatible with the Hardy-Weinberg equilibrium." (PMID 20102604, 2010).
gastroschisis (1 paper, 2024). Gastroschisis is marked by viscera protruding, without a covering sac, from the fetal abdomen on the right lateral base of the umbilicus. "Padula investigated 75 genetic variants in 20 genes and found 11 gastroschisis-associated variants in NOS3, ADD1, GNB3, ICAM1, ICAM4, ICAM5, and NAT1 genes." (PMID 39728087, 2024).
Hepatitis B (1 paper, 2012). "GNB3 825T is associated with improved cellular responses to Hepatitis B vaccination, and the 825CC genotype may confer a poor response to interferon α/ribavirin therapy in Hepatitis C infection as well as increased risk of infant death due to infection." (PMID 22214232, 2012).
HIV-1 infection (1 paper, 2012). The type species of lentivirus and the etiologic agent of acquired immunodeficiency syndrome (AIDS). "To date, no data are available to support or oppose these associations in additional cohorts, and it is still unknown whether GNB3 genotype also influences susceptibility to HIV-1 infection." (PMID 22214232, 2012). "GNB3 825T allele carriers demonstrate increased SDF-1α-mediated lymphocyte chemotaxis (a process mediated by G protein signaling); therefore, we wondered whether CXCR4 ligand SDF-1α or CCR5 ligand MIP-1β would be differently expressed between GNB3 genotypes, particularly during HIV-1 infection." (PMID 22214232, 2012). "The paucity of studies investigating the impact of GNB3 polymorphism among African populations and the lack of mechanistic studies make it difficult to assess the true biological significance of this polymorphism in HIV-1 infection." (PMID 22214232, 2012).
influenza (1 paper, 2022). An acute viral infection of the respiratory tract, occurring in isolated cases, in epidemics, or in pandemics; it is caused by serologically different strains of viruses (influenzaviruses) designated A, B, and C, has a 3-day incubation period, and usually lasts for 3 to 10 days. "(F) Representative immunostaining for Gnb3 (Tuft-1 signature) in the Trpm5-GFP reporter mice 35 days post influenza." (PMID 36073526, 2022).
insomnia (1 paper, 2018). A sleep disorder characterized by difficulty in falling asleep and/or remaining asleep. "Antipsychotic-induced restless legs syndrome was linked to polymorphisms located on CLOCK, BTBD9, GNB3, and TH genes, clozapine-induced somnolence was correlated with polymorphisms of HNMT gene, while insomnia was associated with variants of the MTNR1 gene." (PMID 29587340, 2018).
Left ventricular dilatation (1 paper, 2023). Enlargement of the chamber of the left heart ventricle. "A Cox regression analysis adjusted for all other potential modifiers of the risk of abnormal increase in LVEDD corresponding to left ventricular dilatation found that the TT genotype of GNB3 was still an independent risk factor." (PMID 37894940, 2023). "In the subgroup of male patients left ventricular dilatation with abnormally increased LVEDD values occurred significantly more frequently in TT genotypes of GNB3 than in CT/CC genotypes (p = 0.007)." (PMID 37894940, 2023). "Thus, the association between the abnormal increase in LVEDD indicating left ventricular dilatation and the TT genotype of GNB3 seems to be relevant only in elderly patients." (PMID 37894940, 2023). "In this way, this high-risk group of male TT genotype carriers was not protected from the development of left ventricular dilatation with abnormally increased LVEDD values due to the TT genotype of GNB3." (PMID 37894940, 2023).
medulloblastoma (1 paper, 2014). A malignant, invasive embryonal neoplasm arising from the cerebellum. "Some individual members of these pathways, including GNB3, GNB5, GABRA5, RCVRN and SAG were exclusively over-expressed in Group 3 medulloblastoma." (PMID 25412507, 2014).
transitional cell carcinoma (1 paper, 2022). A malignant neoplasm arising from the transitional epithelium, usually affecting the urinary bladder, ureter, or renal pelvis. "GNB3 and IL4 are both enriched in kidney diseases, transitional cell carcinoma, and neoplasm metastasis." (PMID 35565241, 2022).
transitional cell carcinoma of the bladder (1 paper, 2022). "Other enriched genes we found (AR, GNB3, HHLA2 and IL4) were related to transitional cell carcinoma of the bladder (also known as Urothelial carcinoma)." (PMID 35565241, 2022).
vesicoureteral reflux (1 paper, 2017). Abnormal flow of urine from the urinary bladder back into the ureters. "The aim of this study was to establish the relationship of selected polymorphisms: 14094 polymorphism of the ACE, polymorphism rs1800469 of TGFβ-1, rs5443 gene polymorphism of the GNB3 and receptor gene polymorphism rs5186 type 1 AGTR1 with the occurrence of the primary vesicoureteral reflux." (PMID 27988909, 2017).
cardiovascular disease (10 papers, 2012 to 2023). "There are also known studies that have been linking a gene polymorphism rs5443 GNB3 with greater risk of cardiovascular disease and Alzheimer’s predisposition or the development and progression of cancer." (PMID 27988909, 2017). "However, previous reports have described sex-specific effects of the c.825C > T single-nucleotide polymorphism of GNB3, showing that the TT genotype is linked to poorer outcomes of cardiovascular disease among male subjects." (PMID 37894940, 2023). "Indeed, the isolated influence of the GNB3 polymorphism on cardiovascular diseases appears to be mild." (PMID 36077181, 2022). "Esmolol, which is currently used in the treatment of cardiovascular disease, has been predicted as a co-targeted agent targeting Chrna2 and Gnb3." (PMID 38089628, 2023).
tumor (10 papers, 2022 to 2025). "The expression of ATP1A3 and GNB3 in tumor tissues was significantly higher than that in normal tissues." (PMID 36237326, 2022). "In contrast, GNB3 is upregulated in tumours and plays a critical role in cellular signalling." (PMID 40429821, 2025). "The expression of GNB3 changed in TCGA CRC tumor tissues compared to control tissues." (PMID 35373932, 2022). "In summary, our work suggests that the molecular subtype of epithelial tumour cells in TETs determine their tumour immune microenvironment, thus GNB3 and CHI3L1 might predict the immunological behavior and hence prognosis of these tumours." (PMID 36115836, 2022). "Finally, we conducted a gene network analysis of the DEFA gene and found that there were tumor-suppressor-related genes associated with DEFA, including FGF21 and ITLN1, as well as tumor-promoting genes associated with DEFA, including GNB3, CRB2, DIO3, HPD, and Dll3." (PMID 41009818, 2025). "We demonstrate that a subset of tumor cells, featuring medullary thymic epithelial cell (TEC) phenotype and marked by KRT14/GNB3 expression, accumulate in type 1 TETs, while T-cell positive selection is inhibited." (PMID 36115836, 2022). "First, we selected representative genes that represented the unique epithelial cell type in each TET type based on scRNA-seq results and found that GNB3 and CHI3L1 were highly expressed in tumor cells of type 1 and type 3 TETs, respectively." (PMID 36115836, 2022). "On the other hand, a decrease in eigenvector centrality indicates that a gene is connected to less influential or weakening genes, possibly resulting in lower relative influence scores or reduced significance in the network, such as ANXA1, GNB3, POMC, GPER1, and TIMP1 in tumor samples." (PMID 40626556, 2025).
cancer (7 papers, 2017 to 2025). A tumor composed of atypical neoplastic, often pleomorphic cells that invade other tissues. "Additionally, GNB3 is involved in the activation of intracellular signalling pathways related to cancer progression and metastasis." (PMID 40429821, 2025). "In CPTAC-ccRCC, the protein expression of genes AR, GNB3, HHLA2, LIMCH1, and SAA1 had statistical significance in some comparisons of normal samples and cancer stage (Figure A9a–e)." (PMID 35565241, 2022). "GNB3, TRH, and TYMS also play important roles in human cancers." (PMID 35494074, 2022).
retinal disorder (3 papers, 2011 to 2024). Any disease or disorder of the retina. "We previously reported a mutation (D153del) in the GNB3 gene, which causes a recessive, progressive retinal dystrophy known as retinopathy globe enlarged (rge OMIA 2724) in chickens." (PMID 21887213, 2011). "A naturally occurring mutation ‘D153del’ in the GNB3 gene causes the recessively inherited blinding phenotype retinopathy globe enlarged (rge) disease in chickens." (PMID 21887213, 2011).
infection (2 papers, 2012 to 2016). The state of being infected such as from the introduction of a foreign agent such as serum, vaccine, antigenic substance or organism. "Given that 825TT patients are known to exhibit enhanced SDF-1α-mediated chemotaxis, we wondered whether plasma chemokine levels might vary between GNB3 genotype during infection." (PMID 22214232, 2012).
kidney diseases (2 papers, 2022). "We identified six genes enriched to kidney diseases and ccRCC (AR, DPP6, GNB3, IL4, SAA1, SEMA3G)." (PMID 35565241, 2022).
neurological disease (2 papers, 2016 to 2024). "For example, Gnb3 encodes a G protein subunit involved in neurotransmitter signaling and has been associated with an increased risk of neurological disorders." (PMID 38338822, 2024). "Interestingly, three hub genes (ENO3, ISOC1 and GNB3) in this cluster were enriched in the first annotation (hereditary disorder) and/or the second annotation (neurological disease) of diseases and functions." (PMID 27462267, 2016).
gastrointestinal disorders (1 paper, 2010). "Hereditary factors of functional gastrointestinal disorders may be at least partially explained by the GNB3 polymorphism." (PMID 20102604, 2010).
infectious disease (1 paper, 2012). A disorder directly resulting from the presence and activity of a microbial, viral, or parasitic agent in humans. "Compared to other chronic diseases, few studies have examined the impact of the GNB3 SNP on immune function and susceptibility to infectious diseases, particularly HIV." (PMID 22214232, 2012).
GNB3 also shares sentences with these, for which no sentence is quoted: essential hypertension (10 papers); atherosclerosis (5); coronary artery disease (3); age-related macular degeneration (2); chronic kidney disease (2); Cluster headache (2); congenital stationary night blindness (2); dementia (2); Glucose intolerance (2); irritable bowel syndrome (2); peripartum cardiomyopathy (2); prostate carcinoma (2); acute myocardial infarction (1); albinism (1); brain disease (1); cholangiocarcinoma (1); chronic obstructive pulmonary disease (1); colon cancer (1); colorectal cancer (1); cone-rod dystrophy (1); connective tissue disease (1); Dialysis (1); dyslipidaemia (1); food allergy (1); glioma (1); Hepatitis C infection (1); Hirschsprung disease (1); hypercholesterolaemia (1); hypertriglyceridaemia (1); hyperuricaemia (1).
A further 16 diseases each share a sentence with GNB3 in 1 paper.